KRI1 (KRI1 homolog)
Synonyms: FLJ12949
Tractability: PROTAC: ubiquitination databases record sites on it; its protein half-life has been measured.
Gene: Protein-coding gene on chromosome 19 (10,553,085 to 10,566,031, reverse strand). Ensembl gene ENSG00000129347.
Subcellular location (Human Protein Atlas): Nucleoli
Gene Ontology:
Molecular function: RNA binding
Biological process: endonucleolytic cleavage in ITS1 to separate SSU-rRNA from 5.8S rRNA and LSU-rRNA from tricistronic rRNA transcript (SSU-rRNA, 5.8S rRNA, LSU-rRNA)
Cellular component: nucleolus; 90S preribosome
Genetic constraint (gnomAD): Loss-of-function variants: 81 observed, 91.8 expected, observed/expected ratio (o/e) 0.88, 90% interval 0.74 to 1.06. The upper end of that interval is the gene's LOEUF score, 1.06, which puts it in group 4 of 6, group 1 being the genes least tolerant of losing a copy. Missense variants: 868 observed, 886.89 expected, observed/expected ratio (o/e) 0.98, 90% interval 0.93 to 1.03. Synonymous variants: 351 observed, 348.44 expected, observed/expected ratio (o/e) 1.01, 90% interval 0.92 to 1.1.
Homologues: Orthologues: chimpanzee KRI1 (98% identical), macaque KRI1 (96% identical), pig KRI1 (87% identical), dog KRI1 (87% identical), guinea pig KRI1 (82% identical), mouse Kri1 (82% identical), rat Kri1 (82% identical), rabbit KRI1 (77% identical), tropical clawed frog kri1 (59% identical), zebrafish kri1 (55% identical), Drosophila melanogaster CG5645 (42% identical), Caenorhabditis elegans F54C9.9 (37% identical).
Diseases named in the same sentence as KRI1 in open-access papers:
KRI1 is named in the same sentence as 14 diseases in open-access papers, as found by Europe PMC text mining. Sharing a sentence is not in itself a finding about the gene and the disease. The quoted sentences say what the papers report.
cerebral cavernous malformation (5 papers, 2010 to 2022). A disorder characterized by malformations in the structure of the capillaries in the brain. "KRI1 is an ortholog of KRIT1, and KRIT1 mutation has been identified in cerebral cavernous malformations." (PMID 35813863, 2022). "KRI-1 acts via the conserved adaptors ICAP-1 and CCM-2, which, like KRI-1, are linked to cerebral cavernous malformation by curtailing the activity of the ERK-5 MAP kinase pathway, the overactivation of which inhibits KLF-3." (PMID 35137093, 2022).
anemia (2 papers, 2024 to 2025). A reduction in the number of red blood cells, the amount of hemoglobin, and/or the volume of packed red blood cells. "In human diseases, the KRI1 mutation may be relevant with severe iron deficiency anemia." (PMID 38789412, 2024). "kri1 was identified as a plausible pre-rRNA processing factor and then found taking place in apoptosis and cell arrest processes, autophagy, and even intestinal bleeding in cases of severe anemia." (PMID 41465363, 2025).
lymph node metastasis (2 papers, 2022 to 2024). "And KRI1 were significantly correlated with esophageal carcinoma tumor location, lymph node metastasis, and age of patients." (PMID 38789412, 2024). "High expression of KRI1 and BCAP31 predisposed to lymph node metastasis in patients under 60 years of age." (PMID 35813863, 2022). "Five ferroptosis-related genes (TNKS1BP1, AC019100.7, KRI1, BCAP31, and RP11-408E5.5) were found to be significantly correlated with radiographic evidence of lymph node metastasis." (PMID 35813863, 2022). "The TNKS1BP1, AC019100.7, KRI1, BCAP31, and RP11-408E5.5 genes were found to be significantly correlated with esophageal tumor location, radiographic evidence of lymph node metastasis, and age." (PMID 35813863, 2022).
breast carcinoma (1 paper, 2017). "The 3′ member of the KRI1-ATRX fusion (ATRX) has been previously associated with childhood neuroblastoma and the 3′ member of the CACNA1D-CTNNBL1 fusion (CTNNBL1), is associated with an anti-apoptotic, tumor suppressive function consistent with its reduced expression in our breast cancer samples." (PMID 28851357, 2017).
tumor (3 papers, 2017 to 2024). "Furthermore, TNKS1BP1, AC019100.7, KRI1, BCAP31, and RP11-408E5.5 genes were significantly correlated with ESCA tumor location, lymph node metastasis, and patient age." (PMID 35813863, 2022). "Furthermore, TNKS1BP1, AC019100.7, KRI1, BCAP31, and RP11-408E5.5 were significantly correlated with ESCA tumor location, lymph node metastasis, and age of patients." (PMID 35813863, 2022).
cancer (2 papers, 2017 to 2018). A tumor composed of atypical neoplastic, often pleomorphic cells that invade other tissues. "Two of the fusions (ZBTB47-FGD1 and KRI1-ATRX) displayed a > 2.5-fold increase in expression in cancer relative to the normal samples." (PMID 28851357, 2017). "For example, the KRI1-ATRX fusion transcript is the most frequently observed fusion transcript in our dataset (present in nine cancer and one normal samples)." (PMID 28851357, 2017). "When running CBaSe on our pan-cancer dataset, five out of nine genes detected as significant by CBaSe were also detected as significant by SSB-dN/dS (BCL2L12, TERT, AP2S1, KRI1, TMEM214)." (PMID 29855388, 2018).
bacterial infection (1 paper, 2026). "We find also that kri-1/KRIT1 is required for host tolerance to bacterial infection, fecundity, and normal development." (PMID 42239296, 2026).
KRI1 also shares sentences with these, for which no sentence is quoted: COVID-19 (1 paper); esophageal carcinoma (1); esophageal tumor (1); Iron deficiency anemia (1); male infertility (1); neuroblastoma (1); osteoarthritis (1).